STAT1 (signal transducer and activator of transcription 1)
Diseases named in the same sentence as STAT1 in open-access papers (continued):
Sharing a sentence is not in itself a finding about the gene and the disease.
viral infection (continued). "These pathways are closely related to the ability to respond to viral infections, and many downstream genes of JAK/STAT1/2-ISGs signaling, including Oas2, Ifit1, and MX1, which have anti-viral activities." (PMID 36599833, 2023). "The well-characterized importin alpha (IMPA) and importin beta (IMPB) nuclear import pathway plays a crucial role in the innate immune response to viral infection by mediating the nuclear import of transcription factors such as IRF3, NFκB, and STAT1." (PMID 38201275, 2023). "Our study has established that in the white matter of untreated HAND subjects, the expression of STAT1, IFIT3, and ISG15 was upregulated as expected due to viral infection." (PMID 36841839, 2023). "The viral infection also hinders IFN type I by preventing the phosphorylation of tyrosine kinase 2 (TYK2) and inhibiting the activation of STAT1 and STAT2." (PMID 37242305, 2023). "Mechanistically, SerpinA5 can upregulate the phosphorylation of STAT1 and promote its nuclear translocation, thus effectively activating the transcription of IFN-related signaling pathways to impair viral infections." (PMID 36982532, 2023). "In our data, the enriched pathways were related to viral infections such as influenza A (MX1, OAS1, OAS2, OAS3, RSAD2, STAT1) and measles (MX1, OAS1, OAS2, OAS3, STAT1)." (PMID 35464437, 2022). "During viral infection, IFN-1 cytokine binding to its respective IFN receptor (IFNAR1/2) triggers STAT1 and STAT2 phosphorylation and heterodimerization." (PMID 35572196, 2022). "The STAT1 protein can be activated by molecules such as interferon-α, EGF, and IL6 and participate in the immune response to viral infection." (PMID 35928229, 2022). "IRF1 transcriptionally induced by the phosphorylated STAT1 and stabilized by XAF1 further facilitates the induction of the IRF1 target genes such as DDX58, DDX60, MX1, and OAS2 during viral infection." (PMID 35972291, 2022). "This prompted us to test for interactions of vIRF-1 with other members of the STAT family, specifically STAT1 and STAT2, as mediators of innate immune signaling and therefore of central importance to regulation of viral infection and replication." (PMID 35776779, 2022). "It is known that lncRNA Malat1 can inhibit the production of type I IFN in macrophages after virus infection, and lncRNA Sros1 can promote IFN-γ–STAT1 mediated innate immunity." (PMID 33766129, 2021). "Secreted IFN-α/β bind to IFNAR to activate the Stat1–Stat2 heterodimer and induce expression of TRIM22, thereby protecting the host against diverse viral infections." (PMID 34068322, 2021). "For instance, during viral infection, the PARP9/DTX3L complex targets histone H2BJ by interacting with signal transducer and activator of transcription 1 (STAT1)." (PMID 34513839, 2021). "STAT1 and IRF7 are particularly important during virus infections because of their prominent role in regulating antiviral functions." (PMID 34653236, 2021). "LncRNA has antiviral activity, modulates viral replication and growth, and alters IFN and/or ISG expression possibly by interacting with transcription factors STAT1, STAT3, NFκB, and IRFs in response to several viral infections and has been reviewed recently." (PMID 34940755, 2021). "These inhibitors were incubated with the cells 2 h before viral infection, and then endogenous IFN-α, IFN-β, STAT1, IRF7, and OAS1 mRNA expression were examined by qRT-PCR analysis at 24 hpi." (PMID 35062253, 2021). "Of note, background levels of pY-STAT1 and total levels of STAT1 and STAT2 were observed as being increased following virus infection in several analyses." (PMID 32272626, 2020). "As summarized in this review, Tfh cell-related transcription factors including Bcl6, IRF4, STAT1/STAT4/STAT5, T-bet, TCF-1, LEF-1, TOX2, Bach2, FOXP1, and KLF2 are all involved in the virus infection." (PMID 32766317, 2020).
viral infection (continued). "STAT1 signaling is important for the generation of Th1 polarized cells, as well as the production of IFN-γ during viral infection, both of which are essential for recovery and viral clearance." (PMID 32397226, 2020). "During the early phase of viral infections, STAT4 becomes activated initiating a fast IFN-γ response followed by STAT1 activation, which replaces STAT4 at the IFNAR receptor decreasing the ability to produce IFN-γ." (PMID 31781102, 2019). "Mechanically, after viral infection, MHC I enhanced SHP2 activation, which suppressed STAT1 phosphorylation and led to reduced ISG production." (PMID 31583257, 2019). "Given that several studies demonstrated protective roles for inflammasomes in various viral infections, our observation that the Nlrp3 inflammasome contributes to MNV-induced lethality in Stat1-/- mice is remarkable." (PMID 31017981, 2019). "We next investigated the effects of NSs expression on STAT1 subcellular location and translocation in response to IFN-γ in the context of viral infection." (PMID 31191546, 2019). "Together, our results suggest that NDR1 promotion of STAT1 translation is an important event for IFN-dependent antiviral immune response, and suggest that NDR1 has an important role in controlling viral infections." (PMID 30018336, 2018). "STAT1 is an important transcription factor to promote IL-6-dependent Bcl6 induction and TFH differentiation during the DC priming stage of acute viral infections." (PMID 30057920, 2018). "Whatever the effect of STAT1 and STAT3 heterodimers on viral infection, either proviral or antiviral, it provides another layer of potential manipulation for viral gene products that warrants further research." (PMID 29543893, 2018). "During viral infection, type I IFN signaling through IFNAR induces STAT1/STAT2 activity, but also leads to the induction of STAT3, which is thought to provide negative feedback keeping the IFN response under control." (PMID 30473701, 2018). "Type I interferons (IFNα and IFNβ) activate STAT1 and STAT2 proteins via phosphorylation and are required for early control of a viral infection." (PMID 27178303, 2016). "Driver genes of this sub-network (OAS2, ISG15, STAT1, and ADAR) are involved in immune response to viral infections, and expression of these genes is inducible by interferon." (PMID 25868721, 2015). "Several interferon-inducible genes involved in immune response to viral infection (including OAS2, ISG15, STAT1, and ADAR) were identified as “drivers” in this sub-network based on the ARACNE and key driver analysis." (PMID 25868721, 2015). "Taken together, these results show that the IFN produced and secreted by U373MG-PMLIV cells 20 h post-VSV infection, activates STAT1, induces ISG products and protects HeLa cells from viral infection." (PMID 24586174, 2014). "IRF3 and IRF7 have been implicated as positive regulators of IFN-I gene expression induced by virus infections, whereas IRF9 constitutes an IFN-stimulated gene factor 3 together with STAT1 and STAT2, and is responsible for the induction of the IRF7 gene." (PMID 24903089, 2014). "Pivotal components of the IFN response to virus infection include the IFN receptors (IFNR), and the downstream factor signal transducer and activator of transcription 1 (Stat1)." (PMID 21915277, 2011). "In response to viral infection, Ag-specific CD8+ T cells express peak levels of STAT1 for a shorter period of time than CD4+ cells." (PMID 20436908, 2010). "The activated STAT1 in turn regulates the expression of several STAT1-dependent genes, including genes involved in growth control and that mediate the responses of IFN types (for example, IFN-γ) to viral infections and other pathological agents." (PMID 20964825, 2010). "STAT1, which plays a significant role in JAK-STAT signaling pathway and has been reported to be involved in host immune response to virus infections, was found to be differentially expressing between the two virus infections in our study." (PMID 20828378, 2010).
viral infection (continued). "STAT1 is translocated to the nucleus and triggers the transcription of interferon-stimulated genes (ISGs), such as Interferon Regulatory Factor-1 (IRF1), which play a key role in the host’s defense against viral infections." (PMID 41596343, 2026). "Upregulation of the Stat1-mediated response to the virus, interferon response, immune system activation, and interferon-stimulated genes (ISGs; e.g., Rsad2, IFITM3, Cxcl9, Bst2, and Oas2) across all strains confirmed ongoing viral infection." (PMID 39875898, 2025). "STAT1, by transmitting IFN signals, facilitates the transcription of genes with critical antiviral properties, playing a central role in the immune reaction to viral infection." (PMID 40920886, 2025). "FAH was identified as a candidate host factor that contributes to the control of viral infection independent of STAT1, and its metabolite, DMF, exhibited antiviral activity." (PMID 40048440, 2025). "Upregulation of the Stat1-mediated response to the virus, interferon response, immune system activation, and ISGs, such as Rsad2, IFITM3, Cxcl9, Bst2, and Oas2, across all strains confirmed ongoing viral infection." (PMID 39875898, 2025). "HSTAT1 was readily cleaved in the infected cells, as evidenced by a reduction in the protein level of STAT1-HA, whereas the protein level of mSTAT1 was not significantly affected upon viral infection." (PMID 38018976, 2024). "Next, we studied in detail the host-induced reaction to viral infection on a transcriptomic level, seeing that iPNs have an intrinsic expression of the core ISGs like ADAR, STAT1, STAT2, or CD47, which was confirmed with publicly available single-cell datasets." (PMID 39546567, 2024). "STAT1 activation is dependent on Syk rather than cytokine-activated JAK signaling at the early stage of viral infection, which is important for early antiviral immunity." (PMID 36834974, 2023). "Thus, STAT1 GOF can alter IFN signaling in NK cells, contributing to their dysfunction during viral infection." (PMID 36826612, 2023). "Thus, the balance between STAT1 and STAT4 activation in NK cells would be altered during viral infections." (PMID 36826612, 2023). "The contrast between AR STAT1 and IRF1 deficiencies is striking in this respect, as the two patients with IRF1 deficiency did not suffer from the life-threatening viral diseases seen in patients with AR complete STAT1 deficiency." (PMID 36736301, 2023). "Viral infections generated IFNs, which were accompanied by the transcription of OASL, and activated IFN responsive pathways after upregulating IFN regulated genes including OAS1 and STAT1." (PMID 36765396, 2023). "Aside from STAT1, the nucleocytoplasmic trafficking of other key innate immunity signal transducers, such as IRF3 and NF-κB (p50/p65), is also critical for the activation of host innate immune response upon viral infection." (PMID 38203469, 2023). "The inhibitory effect of these additional viral proteins on STAT1 translocation can only be rescued by high concentration of artificial IFN treatment but not by IFN induced by viral infection." (PMID 37377442, 2023). "In this study, knockdown of LINC02574 in A549 cells attenuated the expression of multiple ISGs and type I and type III IFNs, as well as the activation of STAT1 triggered by IAV infection, indicating that LINC02574 positively regulates the innate immune response to viral infection." (PMID 37108410, 2023). "Upon activation of ifn receptors by ligands, STAT1 and STAT2 are phosphorylated and form ISGF3 complex with IRF9, which is shuttled into the cell nucleus to trigger the expression of ISGs involved in immune response against viral infection." (PMID 35392096, 2022). "Abnormality in the IFN-signalling cascade, for example, the absence of signal transducer and activator of transcription 1 (STAT1), will lead to the failure of activating ISGs, making the host cell highly susceptible to virus infections." (PMID 36399061, 2022).
viral infection (continued). "We did not detect phosphorylation of IRF3 and STAT1 in A549 cells of RUNX1 knockdown or overexpression without virus infection." (PMID 35248104, 2022). "Up-regulated differentially expressed genes (DEGs) indicated a clear relationship with the innate immune response against viral infection, including genes coding PRRs (LPG2 or DHX58) and IFN-stimulated genes (ISG15, Mx, STAT1, HERC5, IFI44, IFIT-1, NUP133, TRIM21)." (PMID 35215144, 2022). "While EGFR inhibition by gefitinib did not impact STAT1, it was interestingly able to rescue the otherwise decreased levels of STAT2 phosphorylation caused by vanadate/virus infection." (PMID 35572196, 2022). "Our previous studies have shown that STAT1 can be activated through RIG-I/MAVS/Syk pathway at the early stage of viral infection, which is independent of cytokines and JAK signaling pathways." (PMID 36148221, 2022). "AD STAT1 deficiency manifests frequently as MSMD, virus infection in three cases, and bacterial or fungal infection in none." (PMID 36339330, 2022). "IFN-I, including IFN-α and IFN-β, further triggers the phosphorylation of TFs STAT1 and STAT2 via the JAK-STAT pathway to induce over 300 IFN-stimulated genes (ISGs), which synergistically inhibit viral infection by targeting almost all the steps of viral life cycles." (PMID 35972291, 2022). "The fact that IAV increased ACE2 expression is not surprising, since viral infections can increase ACE2 mRNA transcription via transcription factors such as STAT1 as part of the IFN signalling response." (PMID 33419885, 2021). "In addition, STAT1 is a downstream gene of JAK2 in IFN-gamma signaling pathways, which can infer the significance of JAK2 in viral infection." (PMID 34199353, 2021). "A protective role against viral infection has also been reported for STAT1/2 and IRF136; these findings have not yet been reported in SLE or DM." (PMID 34848794, 2021). "Intriguingly, we found that viral infection did not impact STAT1 and STAT2 expression and only slightly decreased IFN-I-mediated STAT phosphorylation." (PMID 33097660, 2020). "During the onset of viral infection, the type 1 interferon (IFN1) and cytokines are promptly induced against the viral infection, whereas 3Cpro is involved in the inhibition of IFN-α/β by blocking the nuclear translocation of STAT1/STAT2." (PMID 33255534, 2020). "When cellular HOIP was knocked out, viral infection was no longer able to upregulate STAT1 linear ubiquitination." (PMID 32123171, 2020). "As well, expression of STAT1 has a non-redundant role for survival, regulating a Bcl2-independent mechanism enabling NK cells to evade cell death after viral infection." (PMID 31681330, 2019). "During the course of viral infection, the expression of STAT4 and STAT1 follows an opposite fate." (PMID 31681330, 2019). "Moreover, ISG15, STAT1, IRF7 and DDX58 were identified as the hub genes that play a pivotal role in response to viral infection and their expression were up-regulated with ageing." (PMID 30641486, 2019). "It is not surprised as to STAT1 mRNA upmodulation because STAT1 itself is an ISG which can be most often induced by virus infections unavoidably." (PMID 31191546, 2019). "It was also reported that STAT1 exerts its effect on promoting ISG production via an ubiquitin ligase complex PARP9-DTX3L, which targets host histone H2BJ and viral 3C protease to control viral infection." (PMID 31861316, 2019). "Phosphorylated STAT1 and STAT2 then bind with IRF9 to form a complex called IFN-stimulated gene factor 3 (ISGF3) to initiate the transcription of hundreds of genes that act to block viral infection." (PMID 30840887, 2019). "Some anti-fibrotic factors, namely SMAD6, SMAD7, STAT1, and HGF, were also induced by the virus infection, although to a lesser extent compared to pro-fibrotic upregulation, perhaps as a counterbalance of the potent pro-fibrotic expression induced in vitro by virus infection." (PMID 31878218, 2019).
viral infection (continued). "Combined with our original discovery of an MCOLN2 phenotype in a STAT1−/− background, these data suggest that MCOLN2-mediated enhancement of viral infection is not linked to impairment of IFN or ISG induction." (PMID 29382735, 2018). "Regarding upregulated DEGs, a clear relationship with the innate immune response against viral infection was observed, being unigenes detected those coding pattern recognition receptors (PRRs) (DHX58), and IFN-stimulated genes (ISG15, Mx, STAT1, HERC5, IFI44, IFIT-1, NUP133, and TRIM21)." (PMID 30065724, 2018). "This is in accord with IL-6-mediated phosphorylation of STAT1 and inhibition of viral infection in LNCaP-JAK1, but not LNCaP, cells." (PMID 29441069, 2018). "Together, our data demonstrate that viral infection downregulates NDR1 expression, thus counteracting the mutual inhibition between miR146a and STAT1 and resulting in decreased STAT1 expression and impaired ISG expression, thereby allowing viral escape from innate immunity." (PMID 30018336, 2018). "STAT1 expression was observed after viral infection, suggesting that the IFN-induced JAK-STAT signaling was not blocked." (PMID 28075421, 2017). "In addition to STAT1 and STAT2, the other STATs activated by type I IFNs can be inhibited by virus infection, which has been less investigated; the role of other STATs in the IFN-mediated response still requires further investigation." (PMID 29312301, 2017). "Because the total STAT1 activity was not correlated with the cellular responses against viral infection, we examined the heterogeneity of basal STAT1 activity within the whole population." (PMID 27427993, 2016). "Type I IFN is a major agonist for STAT1 activation and ISG expression during the viral infection." (PMID 27427993, 2016). "Consistent with the importance of this pathway in mediating the actions of IFNs, mice with no STAT1 have no innate response to either bacterial or viral infections as a result of dysfunctional IFN signaling." (PMID 20353564, 2010). "Likewise, mice lacking STAT2 also exhibit similar phenotypes seen in STAT1KO mice, implying a pivotal role of STAT1 and/or STAT2 in response to viral infection." (PMID 19272190, 2009). "It appears that induction of STAT1 is not as highly responsive to IFN induced by virus infection as the other component genes of the Type I IFN system in that the fold increase was low compared to the other genes studied." (PMID 18307775, 2008). "Alternatively, the host cell might activate STAT1 rather than IFNα/β to protect against viral infection." (PMID 40001503, 2025). "First, we examined whether Sec10 affected the transcriptional expression of STAT1, and found that overexpression of Sec10 did not affect the mRNA expression of STAT1 induced by viral infection." (PMID 40920886, 2025). "Moreover, STAT1 is essential in the IFN-α-activated JAK/STAT signaling pathway and it induces expression of IFN-stimulated genes (ISGs) which are important in innate immunity against viral infection." (PMID 37409113, 2023). "We also observed elevated transcript levels for several restriction factor-encoding genes (IFIT and IFITMs) and pro-inflammatory factors (STAT1, IRF8) known to be activated in response to viral infections, including HIV-143–45, which may contribute to the EC phenotype." (PMID 38168352, 2023). "STAT1/STAT3 heterodimerization is favoured by IL-27 during viral infections such as HBV and HSV, and may represent an alternative pathway to ISG production, as the STAT1/STAT3 heterodimer is not typically associated with IFN signaling." (PMID 35634328, 2022). "USP22-deficient hIECs strongly upregulate genes involved in IFN signaling and viral defense, including numerous IFN-stimulated genes (ISGs), with increased secretion of IFN-λ and enhanced STAT1 signaling, even in the absence of exogenous IFNs or viral infection." (PMID 35933402, 2022).